FOXM1 (forkhead box M1)
Diseases named in the same sentence as FOXM1 in open-access papers (continued):
Sharing a sentence is not in itself a finding about the gene and the disease.
esophageal squamous cell carcinoma (13 papers, 2017 to 2025). Esophageal squamous cell carcinoma (ESCC) is a type of esophageal carcinoma (EC) that can affect any part of the esophagus, but is usually located in the upper or middle third. "UBE2S, HIF‐1α, and FOXM1 in esophageal squamous cell carcinoma and their relationship with clinicopathological features." (PMID 41427004, 2025). "Circular RNA hsa_circ_0069399, derived from the same parental gene, has been shown to enhance esophageal squamous cell carcinoma progression by modulating the microRNA-761/ Forkhead box M1 (FOXM1) axis." (PMID 39048814, 2024). "For example, FOXM1 is a validated transcription factor of UBE2C in esophageal squamous cell carcinoma." (PMID 36765911, 2023). "FOXM1 is overexpressed in a wide range of different solid tumors, including esophageal squamous cell carcinomas (ESCC)." (PMID 29596365, 2018). "We aimed to elucidate the role and molecular mechanisms of FOXM1 in regulating metastasis in oesophageal squamous cell carcinoma (ESCC) as well as its clinical implications." (PMID 30485581, 2019). "Therefore, the aim of this study was to investigate whether UBE2C is a transcriptional target of FOXM1, using esophageal squamous cell carcinoma (ESCC) as a model, in addition to several cancer-deposited data." (PMID 29596365, 2018). "DKK1 knockdown decreased FOXM1 expression and vice versa in PDAC and esophageal squamous cell carcinoma (ESCC) cells." (PMID 34117362, 2021).
nasopharyngeal carcinoma (13 papers, 2017 to 2025). A carcinoma arising from the nasopharyngeal epithelium. "However, the regulatory role and underlying mechanisms of FOXM1 in nasopharyngeal carcinoma (NPC) metabolism remain unclear." (PMID 35656815, 2022). "AGK was also considered to be a promoter of resistance to paclitaxel in nasopharyngeal carcinomas and this chemoresistance properties which eventually mediate tumor growth and metastasis is facilitated by overexpressed FOXM1 via JAK2/STAT3 signaling pathway." (PMID 40176914, 2025). "In our previous study, we proved that FOXM1 promotes drug resistance in nasopharyngeal carcinoma cells by regulating ABCC5 gene transcription." (PMID 35141332, 2022). "Overexpression of ATP-binding cassette C5 transporter (ABCC5) correlates with Forkhead box M1 (FOXM1) in paclitaxel-resistant nasopharyngeal carcinoma cells." (PMID 34502361, 2021). "FOXM1, an oncogenic transcription factor, is a promoter of cell proliferation and accelerated development of breast adenocarcinomas, squamous carcinoma of the head, neck, and cervix, and nasopharyngeal carcinoma." (PMID 37025658, 2023). "In this study, we attempt to investigate the self-renewal and tumourigenicity of FoxM1 and its clinical significance in nasopharyngeal carcinoma (NPC)." (PMID 30416986, 2018). "In nasopharyngeal carcinoma cells, paclitaxel induces ABCC5 expression through the activation of FOXM1, and its blockage re-sensitizes the cells to paclitaxel." (PMID 33632224, 2021).
small cell lung carcinoma (13 papers, 2013 to 2025). Small cell lung cancer (SCLC) is a highly aggressive malignant neoplasm, accounting for 10-15% of lung cancer cases, characterized byrapid growth, and early metastasis. "Previous studies have reported the involvement of FOXM1 in various tumorigenesis and progression processes and have also been related with poor survival rate of small cell lung cancer." (PMID 36498802, 2022). "In our previous study, we have shown that FoxM1 promoted in vitro metastatic ability of small cell lung cancer." (PMID 23536876, 2013). "Moreover, genistein has been reported to alter FoxM1 (forkhead box protein M1) function, which triggers apoptosis and cell cycle arrest in the H446 small cell lung cancer cell line, halting cell proliferation and differentiation." (PMID 38731403, 2024). "For instance, in small-cell lung cancer, miR-1 directly suppresses C-X-C motif chemokine receptor 4 (CXCR4), leading to the subsequent inhibition of FOXM1 and ribonucleotide reductase M2 (RRM2), thereby impeding tumor progression." (PMID 41373864, 2025).
serous ovarian cancer (12 papers, 2013 to 2024). "Specifically, the spliceosome-associated factor CTNNBL1, has been related to proliferation and invasion in HGSOC, at least partially through regulation of FOXM1 splicing, Notably, the FOXM1 signaling pathway is activated in 84% high-grade serous ovarian cancer and linked to platinum resistance." (PMID 35120576, 2022). "Genetic studies implicate the oncogenic transcription factor Forkhead Box M1 (FOXM1) as a potential therapeutic target in high-grade serous ovarian cancer (HGSOC)." (PMID 38704607, 2024). "We previously reported that FOXM1 amplification correlates with FOXM1 mRNA expression in high-grade serous ovarian cancer (HGSC)." (PMID 30795624, 2019). "Pathway analyses suggest that NOTCH and FOXM1 signaling contribute to serous ovarian cancer pathophysiology." (PMID 25537512, 2015). "NOTCH and FOXM1 signaling were involved in serous ovarian cancer pathophysiology." (PMID 27231557, 2014). "FOXM1 expression was remarkably high in testicular germ cell tumors (TGCT), high-grade serous ovarian cancer (HGSC), and basal breast cancer (BBC)." (PMID 30795624, 2019).
endometrial cancer (11 papers, 2016 to 2025). Primary or metastatic malignant neoplasm involving the endometrium (mucous membrane that lines the endometrial cavity). "The high FOXM1 expression in endometrial carcinoma is closely associated with the prognosis, pathological stage, and clinical grade of endometrial carcinoma patients and can thus serve as a marker of endometrial carcinoma prognosis and a candidate target for its treatment." (PMID 37667311, 2023). "Although the biological functions of Forkhead box protein M1 (FOXM1) were explored in a variety of cancer, to date, however, little attention has been paid to the situation of FOXM1 in EC endometrial cancer (EC)." (PMID 37159818, 2023). "Expression of LCN2 in endometrial cancer is facilitated by forkhead box protein M1 (FOXM1)." (PMID 39372215, 2024). "It has been determined that foxM1 is up‐regulated in endometrial cancer." (PMID 33960101, 2022). "FOXM1 may be an attractive therapeutic target and an excellent biomarker for endometrial cancer prognosis." (PMID 34252882, 2021). "Therefore, we measured FoxM1 expression in endometrial cancer tissues and adjacent normal tissues using qRT-PCR." (PMID 29190956, 2017). "In endometrial cancer, SLC27A2 is downregulated by FOXM1, affecting fatty acid metabolism and disease progression." (PMID 40647532, 2025). "The effect of SNORD14E on the FOXM1 exon VIIa skipping was rescued by knocking down SRSF1 in endometrial carcinoma cell lines, suggesting that SNORD14E recognized FOXM1 and promoted the FOXM1 exon VIIa skipping by recruiting SRSF1 in combination with SRSF1." (PMID 37667311, 2023). "In addition, FOXM1 enhances the DDP resistance sensitivity in gastric and endometrial cancers." (PMID 39020302, 2024).
Ewing sarcoma (11 papers, 2013 to 2025). A small round cell tumor that lacks morphologic, immunohistochemical, and electron microscopic evidence of neuroectodermal differentiation. "In line with this, FOXM1 is found to be expressed at elevated levels in both Ewing sarcoma cell lines and primary tumors." (PMID 37894854, 2023). "Treatment with Thiostrepton led to the inhibition of FOXM1 expression, which was accompanied by an increase in apoptosis observed in several Ewing sarcoma cell lines." (PMID 37894854, 2023). "FOXM1 expression was inhibited by treatment with thiostrepton, which paralleled with an increase in apoptosis in a variety of Ewing sarcoma cell lines." (PMID 26258070, 2015). "In agreement with this, FOXM1 is expressed at high levels in Ewing sarcoma cell lines and primary tumors." (PMID 26258070, 2015). "In order to characterize the relevance of FOXM1 in Ewing sarcoma pathogenesis, the authors performed FOXM1 knockdown experiments demonstrating that FOXM1 downregulation correlates with a significant reduction in anchorage independent growth." (PMID 26258070, 2015). "To evaluate a possible role of FOXM1 in Ewing tumor biology, we evaluated microarray data from 56 patients with localized Ewing Sarcoma." (PMID 23365673, 2013). "So FOXM1 appears to be of biologic significance in Ewing tumors in vitro but also can, in principle, be targeted via small molecule inhibition." (PMID 23365673, 2013). "Because of our interest in the role of the GLI1 transcription factors in Ewing tumors, we became intrigued by a possible role for FOXM1 in Ewing tumor development." (PMID 23365673, 2013). "In this paper, we show that FOXM1 is expressed at robust levels in a variety of Ewing tumor specimens and in Ewing cell lines." (PMID 23365673, 2013). "In summary, these results collectively indicate that targeting FOXM1 could also be a potential avenue for Ewing sarcoma treatment." (PMID 37894854, 2023). "Interestingly, they also explored pharmacological approaches aimed at reducing FOXM1 levels in Ewing sarcoma cells, yielding noteworthy results." (PMID 37894854, 2023). "Based on this, some studies have shown that thiazole antibiotics and proteasome inhibitors represented by thiostrepton and Siomycin A may have a role in the treatment of Ewing sarcoma by inhibiting FoxM1 expression." (PMID 35153742, 2021). "FoxM1, an oncogenic factor, is highly expressed in Ewing sarcoma and cell lines." (PMID 35153742, 2021). "In Ewing sarcoma thiostrepton has a dual inhibitory effect on FOXM1 and EWS/FLI mRNA expression." (PMID 27074562, 2016). "Taken together, these findings suggest that targeting FOXM1 may be also an opportunity for Ewing sarcoma treatment." (PMID 26258070, 2015). "Given the role established for FOXM1 in other tumor systems, we undertook to determine whether it plays a similar role in Ewing tumors." (PMID 23365673, 2013). "Along with our shRNA data, this suggests FOXM1 may prove a useful therapeutic target in Ewing tumors." (PMID 23365673, 2013). "Our finding of FOXM1 inhibition by Thiostrepton in Ewing cells suggests that compounds of this class may be of potential utility in the treatment of Ewing tumors." (PMID 23365673, 2013). "Since EWS/FLI1 is the best established driver mutation in Ewing tumors, we sought to determine whether EWS/FLI1 can drive the expression of FOXM1." (PMID 23365673, 2013). "FOXM1 is involved in Ewing tumor pathogenesis and may prove to be a useful therapeutic target in Ewing tumors." (PMID 23365673, 2013). "mRNA expression of PPP1R1A, GLI1, FoxM1, and NR0B1 genes highly expressed in Ewing’s sarcoma cells was dependent on EWS-FLI1." (PMID 36194562, 2022). "CDKN1C and a related member of the FOXO family, FOXO1, have previously been shown to inhibit Ewing Sarcoma growth, while FOXM1, GLI1 and PDGFRB have been shown to be growth-promoting in Ewing Sarcoma." (PMID 30237855, 2018).
Ewing sarcoma (continued). "Our work demonstrated that it reduces in a dose- and in a time-dependent manner the expression of Gli1, NR0B1, FOXM1 and VEGFA, some of the EWS-Fli1 target-genes considered as determining factors in the carcinogenesis of Ewing Sarcoma." (PMID 27006472, 2016). "Interestingly, pharmacological approaches addressed to reduce FOXM1 levels have also been tested in Ewing sarcoma cells with notable results." (PMID 26258070, 2015).
ovarian tumor (11 papers, 2011 to 2025). "The transcription factor ETV5 is significantly upregulated in ovarian tumor samples and transcriptionally activates FOXM1." (PMID 40746724, 2025). "OTUB1 (ovarian tumor domain protease domain-containing ubiquitin aldehyde-binding proteins)-mediated deubiquitination of FOXM1 (Forkhead box M1) participates in carcinogenesis of various tumors." (PMID 32257108, 2020). "A systemic analysis of gene expression profiles in microarrays showed that FOXM1 mRNA was overexpressed in nearly every tumor analyzed, including ovarian tumors." (PMID 25537512, 2015). "FOXM1 mRNA and protein expression were significantly increased in ovarian tumors as compared to the mouse normal ovary control." (PMID 26243836, 2015). "The combination of cisplatin and the FOXM1 inhibitor thiostrepton inhibited the expression of stem cell markers in chemoresistant cells and subcutaneous ovarian tumor growth in mouse xenografts." (PMID 25537512, 2015). "The impairment of metastatic potential of cancer cells by FOXM1 inhibitors underscores its therapeutic value in advanced ovarian tumors." (PMID 21858223, 2011). "Intriguingly, the overexpressed phospho-ERK (p<0.001) and FOXM1 (p<0.001) were significantly correlated to high-grade ovarian tumors with aggressive behavior such as metastasized lymph node (5 out of 6)." (PMID 21858223, 2011). "Moreover, increased ETV5 expression correlates with elevated FOXM1 transcript levels in ovarian tumor samples." (PMID 40746724, 2025). "Meta-analyses of FOXM1 in human solid tumors reported that FOXM1 protein expression in ovarian tumors coincides with an overall hazard ratio (HR) of 1.34 (95% CI = 0.96–1.88) for overall survival and an odds ratio (OR) of 2.34 (95% CI = 1.30–4.20) for 3-year overall survival." (PMID 34205406, 2021). "In addition, it would be important to investigate the in vivo anti-tumor activity of another FoxM1 inhibitor, Siomycin A, and its potential synergistic activity with carboplatin in ovarian tumor xenograft and patient-derived xenograft models." (PMID 25426548, 2014). "Summary of nuclear FOXM1 immunohistochemical staining results in various types of ovarian tumors." (PMID 25411964, 2014). "ZNF385B, previously unrecognized as a potential ovarian tumour marker, and VEGFA correlated with overall and progression-free survival, respectively, whereas TPX2 and FOXM1 with optimal CA125 normalization." (PMID 23029477, 2012).
renal cell carcinoma (11 papers, 2017 to 2025). "These two studies linking Foxm1 to renal tubular epithelial repair were the first to find a role for Foxm1 in kidney injury and repair, as prior studies had looked at FOXM1 only in the context of renal cell carcinoma." (PMID 38916959, 2024). "LINC01094 expression is elevated in renal cell cancer tissues and cells, and LINC01094 overexpression down-regulates miR-577 expression and promotes the translation of FOXM1 mRNA, by which it increases the radioresistance of renal cell carcinoma cells." (PMID 34657558, 2021). "The aim of this study was to explain the effects of microRNA‐132 in renal cell carcinoma by regulating FOXM1 expression." (PMID 31625200, 2020). "The miR-149-5p precursor mitigates cell migration and invasion in renal cell carcinoma by targeting FOXM1." (PMID 33262781, 2020). "It has been shown that PLK1 and FOXM1 expression were positively correlated in renal cell carcinoma cell lines." (PMID 33680951, 2020). "Depending on clinical data, we found that FOXM1 protein expression of renal cell carcinoma tissues was higher than that in adjacent normal tissues." (PMID 31625200, 2020). "We aim to investigate the effect and mechanism of OTUB1/FOXM1 on RCC (renal cell carcinoma) progression." (PMID 32257108, 2020). "miRNA‐132 had anti‐tumor effects in renal cell carcinoma by suppressing FOXM1 expression." (PMID 31625200, 2020).
Sepsis (11 papers, 2012 to 2025). Sepsis is defined as life-threatening organ dysfunction caused by a dysregulated host response to infection. "The FOXM1 expression of mRNAs was increased 21-fold in septic blood, suggesting that the pathogenic pathway of sepsis may also be closely related to FOXM1." (PMID 37238726, 2023). "We observed that sepsis decreased the levels of FOXM1 and its downstream targets, FOXO1, E2F3, and β-catenin but upregulated p21 in lung tissue." (PMID 41253746, 2025). "Rabeprazole improves vascular repair and the resolution of sepsis-induced inflammatory lung injury through the endothelial HIF-1α/FoxM1 signaling axis." (PMID 35563731, 2022). "We previously showed that vascular repair and the resolution of sepsis-induced inflammatory lung injury is dependent upon endothelial HIF-1α/FoxM1 signaling." (PMID 35563731, 2022). "Therapeutic activation of HIF-1α signaling and HIF-1α/FoxM1-dependent vascular repair therefore represents a putative therapeutic strategy for the treatment of inflammatory vascular diseases, such as sepsis and ARDS." (PMID 35563731, 2022). "In conclusion, Rabeprazole is a potent inducer of HIF-1α that promotes vascular repair and the resolution of sepsis-induced inflammatory lung injury via endothelial HIF-1α/FoxM1 signaling." (PMID 35563731, 2022). "Given that endothelial FoxM1 is a critical reparative transcriptional factor mediating vascular repair following sepsis challenge, we next determined the effects of Rabeprazole treatment in Foxm1/Tie2Cre mice." (PMID 35563731, 2022). "The aim of this study was to identify a candidate inducer of HIF-1α/FoxM1 signaling for the treatment of sepsis and ARDS." (PMID 35563731, 2022). "Employing Foxm1/Tie2Cre mice, we demonstrated that Rabeprazole-induced FoxM1 expression was predominantly in lung ECs following sepsis challenge and the induced FoxM1 expression was required for Rabeprazole-induced vascular repair." (PMID 35563731, 2022). "Our previously published study shows that FoxM1 is the downstream target of HIF-1α that is responsible for vascular repair following sepsis challenge." (PMID 35563731, 2022). "FDA-approved drugs that stimulate HIF-1α/FoxM1 signaling, such as Rabeprazole, represent promising candidate therapies for patients with severe sepsis and ARDS." (PMID 35563731, 2022). "Meanwhile, transgenic expression of FOXM1 in lung endothelial cells can repair lung vascular injury and reduce morality induced by various sepsis challenges in mice." (PMID 30992007, 2019). "We have identified the necessary and sufficient role of FoxM1 in promoting endothelial repair and resolution of lung inflammation in a clinically relevant model of sepsis." (PMID 23185540, 2012). "Together, these data suggest FoxM1 expression in endothelial cells is necessary and sufficient to mediate endothelial repair and thereby promote survival following sepsis challenge." (PMID 23185540, 2012). "Together, these data demonstrate the critical role of FoxM1 in mediating endothelial repair following lung vascular injury induced by sepsis." (PMID 23185540, 2012). "Here, employing the FoxM1 transgenic (FoxM1 Tg) mice, we showed that transgenic expression of FoxM1 promoted rapid recovery of endothelial barrier function and survival in a clinically relevant model of sepsis induced by cecal ligation and puncture (CLP)." (PMID 23185540, 2012). "Likewise, the EC regeneration and vascular repair mediated by FoxM1 is considered one of the potential therapeutic pathways for sepsis-induced ARDS." (PMID 40476000, 2025). "Our study provides further evidence that vascular repair and the resolution of inflammatory lung injury is driven by HIF-1α and FoxM1 in ECs and that pharmacological activation of the HIF-1α/FoxM1 signaling axis is a putative therapeutic strategy for severe sepsis and ARDS." (PMID 35563731, 2022).